PTH (parathyroid hormone)
Diseases named in the same sentence as PTH in open-access papers (continued):
Sharing a sentence is not in itself a finding about the gene and the disease.
Hypercalcemia (continued). "This implies that hypercalcemia is more important in the causation of PRES than elevated PTH levels." (PMID 32129057, 2020). "A quick Google search identifies several case reports describing hypercalcemia associated with parathyroid hormone in women with ovarian cancer, including a high-profile study by Nussbaum and colleagues and a more recent one by Ma and colleagues." (PMID 33226347, 2020). "Currently, the goal of therapy for metastatic disease is to control the PTH-driven hypercalcemia which represents the primary cause of mortality." (PMID 32149123, 2020). "PTH was high in all patients, except in six (21.4%) who had hypercalcemia associated with an inappropriate normal PTH level." (PMID 31979085, 2020). "Familial hypocalciuric hypercalcemia (FHH) is a genetic condition associated with hypocalciuria, hypercalcemia, and, in some cases, inappropriately high levels of circulating parathyroid hormone (PTH)." (PMID 32213715, 2020). "Parathyroid hormone (PTH) related hypercalcaemia is most commonly caused by primary hyperparathyroidism (PHPT) and more rarely by familial hypocalciuric hypercalcaemia (FHH)." (PMID 31797261, 2020). "This progressed to secondary hyperparathyroidism by 20 weeks of age, which caused both hypercalcemia and hyperphosphatemia due to accelerated bone resorption by PTH." (PMID 32617522, 2020). "The importance of signaling response duration is underlined by clinical studies showing that intermittent PTH has a higher risk of hypercalcemia than abaloparatide." (PMID 33162940, 2020). "HO reportedly caused by hypercalcemia, tissue hypoxia, changes in sympathetic nerve activity, prolonged immobilization, and disequilibrium between parathyroid hormone and calcitonin." (PMID 33226506, 2020). "PTH-related hypercalcaemia, a common endocrine condition, is most frequently caused by primary hyperparathyroidism (PHPT) and very rarely by familial hypocalciuric hypercalcaemia (FHH)." (PMID 31797261, 2020). "The diagnosis of PHP is classically based on the finding of hypercalcemia in the presence of high (or non suppressed) PTH levels; additional laboratory hallmark features are hypophosphatemia and elevated urinary cyclic adenosine monophospate." (PMID 31074404, 2019). "PHPT is often diagnosed incidentally by biochemical testing that demonstrates hypercalcemia in association with inappropriately increased parathyroid hormone (PTH) levels." (PMID 31263451, 2019). "It is currently used for diagnosing idiopathic infantile hypercalcemia, a rare genetic disorder in which a mutation in CYP24A1 results in severe hypercalcemia and suppressed parathyroid hormone (PTH) levels." (PMID 31640241, 2019). "Primary hyperparathyroidism (PHPT), one of the most common endocrine disorders and the most common cause of hypercalcaemia, is characterised by excessive parathyroid hormone (PTH) secretion, which leads to increased serum calcium (Ca) levels." (PMID 31751311, 2019). "Calcification is enhanced by various risk factors common to CKD such as hyperphosphatemia, hypercalcemia, and high serum PTH." (PMID 30796300, 2019). "Indication for parathyroid surgery for all our operated patients was the presence of elevated PTH (over 7.6 pmol/L) associated with hypercalcemia over the value of 11 mg/dL of total serum calcium, both for symptomatic and asymptomatic PHPT." (PMID 30364322, 2018). "In such patients, PTH synthesis and secretion become autonomous with minimal response to therapeutic agents and is often associated with hypercalcemia." (PMID 30109232, 2018). "The reasons by which hypercalcemia is associated with malignancy are increased parathyroid hormone-related peptide (PTHrP), ectopic or primary PTH secretion, excess of extrarenal activated vitamin D, and multiple concurrent etiologies." (PMID 29890702, 2018).
Hypercalcemia (continued). "Primary hyperparathyroidism (PHPT) is characterized by hypercalcemia and elevated levels of parathyroid hormone (PTH) and is most commonly caused by a single glandular enlargement, or adenoma." (PMID 30367667, 2018). "The parathyroid cancer is a very rare cause of hypercalcemia, which needs to be considered in the differentials of primary hyperparathyroidism, particularly in the setting of high PTH levels." (PMID 30157930, 2018). "Two types of hypoparathyroidism are known: primary hypoparathyroidism, which is a state of inadequate PTH activity, and secondary hypoparathyroidism, a physiologic state in which PTH levels are high in response to a primary process that causes hypercalcemia." (PMID 29794776, 2018). "According to the extensive workup and the post-partum normalization of PTH and calcium levels, we conclude that excessive secretion of placental PTHrP was the cause of hypercalcemia in this patient." (PMID 29694631, 2018). "Intermittent administration of low-dose PTH or PTHrP increases bone formation, whereas continuous infusion of a high dose of PTH or PTHrP causes bone resorption and hypercalcemia." (PMID 30151009, 2018). "Based on the biochemistry results of hypercalcemia, associated with elevated PTH levels, a diagnosis of primary hyperparathyroidism was made." (PMID 30157930, 2018). "Findings from another meta-analysis of randomized controlled trials had suggested that treatment of vitamin D compounds was associated with increased risk of hypercalcemia and hyperphosphatemia while inconsistently reducing parathyroid hormone (PTH) levels." (PMID 30400889, 2018). "Our patient had an elevated 1,25 dihydroxyvitamin D with normal 25 hydroxyvitamin D and low PTH, which means that the hypercalcemia was caused by the increased production of 1,25 dihydroxyvitamin D through the humoral hypercalcemia of malignancy pathway." (PMID 29673407, 2018). "Hyperparathyroidism is a disease that occurs due to increased secretion of parathyroid hormone (mainly PTH) from parathyroid glands and as a result, causes hypercalcemia." (PMID 30723655, 2018). "Reducing use of calcium-based phosphate binders should be considered to trade off for more activated vitamin D prescriptions to avoid the risk of hypercalcemia, inadequately suppressed PTH levels, or low bone turnover disease." (PMID 30400889, 2018). "A study examined the association between stroke and PTH in patients with hypercalcemia, and elevated PTH levels were associated with stroke, the incidence of which was 7.1% in patients with primary hyperparathyroidism." (PMID 28115793, 2017). "The hallmark laboratory findings of PHPT are hypercalcemia in the setting of elevated or inappropriately normal serum PTH level." (PMID 28443817, 2017). "Severe parathyroid hormone (PTH)-suppressed hypercalcemia is challenging and requires multidisciplinary diagnostic and therapeutic approaches to (i) confirm or rule out a malignant cause, (ii) treat it and its potentially dangerous complications." (PMID 29181374, 2017). "Clinical findings of parathyroid carcinoma include neck tumor, high PTH and associated hypercalcemia, and generalized fibrous osteitis." (PMID 28726134, 2017). "Prolonged stimulation of the parathyroid gland leading to autonomous PTH hypersecretion (tertiary hyperparathyroidism) is another cause of hypercalcemia among CKD patients." (PMID 27683096, 2016). "With the prolonged evolution of PHPT and severe deficiency of vitamin D, adenomas can grow and secrete greater levels of parathyroid hormone causing greater hypercalcemia and greater target organ damage, mainly bone and kidney." (PMID 27525132, 2016). "We were able to follow our patient very closely with blood investigations of vitamin D, parathyroid hormone, calcium, and phosphorous levels to determine the causation between high-dose vitamin D therapy and hypercalcemia." (PMID 27277007, 2016).
Hypercalcemia (continued). "Rats develop hypercalcemia in response to a moderate Mg deficiency, whereas humans develop hypocalcemia secondary to hypoparathyroidism and reduced circulating PTH concentration." (PMID 27136580, 2016). "Primary hyperparathyroidism (PHPT) is a benign, but potentially debilitating, disease where hyperfunctioning parathyroid adenoma(s) can lead to elevated parathyroid hormone (PTH) levels with resultant hypercalcemia and associated morbidities." (PMID 25629056, 2015). "In a few percent of cases, hypercalcemia is caused by tumour cells producing 1,25 OH-Vitamin D or parathyroid hormone (PTH)." (PMID 26499069, 2015). "Severe hypercalcemia is unusual in children and can be either caused by elevated parathyroid hormone (PTH) or a PTH-independent mechanism." (PMID 26213611, 2015). "Primary hyperparathyroidism, familial hypocalciuric hypercalcemia, familial hyperparathyroidism and secondary hyperparathyroidism are examples of PTH-mediated causes of hypercalcemia." (PMID 26213611, 2015). "HHM was dismissed by a negative blood test for PTHrP, and hyperparathyrodism from ectopic PTH production, a rare cause of hypercalcemia in cancer, was dismissed by decreased plasma PTH." (PMID 26499069, 2015). "Oversecretion of parathyroid hormone (PTH) causes hypercalcemia, resulting from inappropriate bone absorption and the reabsorption of calcium from the distal tubules in the kidneys." (PMID 24343173, 2015). "An elevated PTH-related peptide in non-PTH mediated hypercalcemia indicates malignancy as the cause of hypercalcemia." (PMID 26199627, 2015). "When parathyroid hormone (PTH) was very high, up to 1000 ng/L, associated with hypercalcemia, the only treatment was subtotal parathyroïdectomy." (PMID 25123022, 2014). "Hypercalcemia and high PTH levels are associated with HPT-JT, andossifying fibromas reportedly occur in 25–50% of HPT-JT cases." (PMID 24678936, 2014). "In a clinical assessment of postmenopausal women, 40 μg/kg daily PTH 1-34 (i.p.)for 21 months caused hypercalcemia in 28% of the subjects." (PMID 24503654, 2014). "The development of these compounds has been undertaken in an effort to find compounds that will suppress PTH in CKD patients with less risk for development of hypercalcemia than that with calcitriol." (PMID 23566108, 2013). "Paricalcitol has more selective activation of VDR in the parathyroid gland over that in the intestine and bone and offers the possibility of minimizing the risk of hypercalcemia and hyperphosphatemia, while still significantly reducing PTH." (PMID 23509710, 2013). "Primary hyperparathyroidism features continuous excessive parathyroid hormone secretion and is associated with hypercalcaemia and bone fragility." (PMID 22967310, 2012). "This case illustrates the significance of recognizing hypercalcemia as a potential clue in detecting underlying colon cancer involving overproduction of PTH-rp." (PMID 29147304, 2012). "Primary hyperparathyroidism occurs due to an excessive and inappropriate secretion of PTH, the hallmark of the disorder is hypercalcaemia." (PMID 23227372, 2012). "Primary hyperparathyroidism results from the overproduction of parathyroid hormone (PTH) by one or more hyperfunctioning parathyroid glands that usually causes hypercalcemia." (PMID 21776381, 2011). "In view of the suppressed PTH levels and hypercalcemia, a wide variety of PTH-independent causes of hypercalcemia were considered." (PMID 21455429, 2011). "Patients with neonatal severe hyperparathyroidism (NSHPT) are homozygous for the calcium-sensing receptor (CaR) mutation and have very high circulating PTH, abundant parathyroid hyperplasia, and severe life-threatening hypercalcemia." (PMID 21966280, 2011). "Patients with NSHPT are homozygous for the CaR mutation and have very high circulating PTH, abundant parathyroid hyperplasia and severe life-threatening hypercalcemia." (PMID 21966280, 2011).
Hypercalcemia (continued). "The result is hypercalcemia associated with inappropriately normal or mildly elevated levels of parathyroid hormone." (PMID 20727133, 2010). "Hypercalcemia in this situations, have been reported to be caused by the tumor secretion of PTH, PTH-related peptide, prostaglandin E2 and glucagon-like peptides." (PMID 20062638, 2009). "Hypercalcaemia causes reduced glomerular filtration rate, increased sodium excretion, depletion of total body water, and suppression of endogenous parathyroid hormone." (PMID 20181207, 2009). "The initial diagnostic work-up for hypercalcaemia includes serum PTH, phosphorus, 25-OH-cholecalciferol and 1,25 OH2-cholecalciferol, and urinary calcium." (PMID 20181207, 2009). "The diagnosis of primary hyperparathyroidism (PHPT) is based on hypercalcemia and elevated levels of parathyroid hormone (PTH); additional laboratory hallmark features are hypophosphatemia and elevated urinary cyclic adenosine monophosphate (cAMP)." (PMID 18291038, 2008). "The ability of this histological form to secrete PTH has been demonstrated during the last 30 years; in fact, hypercalcemia was associated to secretion of PTH due to oxyphil adenomas in only 124 of 142 reported cases." (PMID 18291038, 2008). "Our patient demonstrated total and ionized hypercalcemia, associated with low serum PTH, elevated serum phosphorous and normal renal function." (PMID 18691418, 2008). "During the third phase there was a recurrence of hypercalcemia associated with elevated parathyroid hormone (PTH) levels and loss of bone mass." (PMID 18021421, 2007). "The critical branching point in the diagnostic workup of hypercalcemia is PTH measurement to determine whether hypercalcemia is PTH‐mediated." (PMID 41567516, 2026). "The diagnostic workup for hypercalcemia typically begins with measuring PTH levels." (PMID 40284609, 2025). "Cinacalcet helps to manage hypercalcemia caused by PC by suppressing PTH secretion; however, its effectiveness may be limited in advanced tumors that do not express the calcium-sensing receptor." (PMID 40806850, 2025). "Low-normal or suppressed PTH narrows down the PTH-independent causes, which can be roughly divided into the three most frequent groups of (i) malignancy-associated, (ii) drug-related, or (iii) vitamin D-mediated hypercalcemia." (PMID 41009532, 2025). "The recovery of parathyroid hormone (PTH) functionality, along with an incorrect parenteral phosphorus supplementation, could be associated with hypercalcemia between the fourth and eighth day of the newborn’s life." (PMID 40077645, 2025). "Jansen's metaphyseal chondrodysplasia (JMC) is an ultra-rare autosomal dominant disease that is caused by heterozygous, activating PTH1R mutations resulting in PTH- and PTHrP-independent hypercalcemia and hypercalciuria, leading to nephrocalcinosis and impaired renal function later in life." (PMID 39950977, 2025). "Maternal hypocalcemia can cause fetal parathyroid hyperplasia and skeletal changes, while maternal hypercalcemia may suppress fetal parathyroid hormone production, causing neonatal hypocalcemia." (PMID 40958864, 2025). "In the case of hypercalcemia caused by hyperparathyroidism, it is postulated that parathyroid hormone plays a role in the pathogenesis of pancreatitis by inhibiting pancreatic vascularisation or by causing the formation of microthrombi, leading to necrosis of the pancreatic parenchyma." (PMID 40944062, 2025). "While calcitriol and paricalcitol consistently suppress PTH, calcifediol may represent a promising alternative with a lower risk of hypercalcemia, although comparative meta-analyses are still needed." (PMID 41155582, 2025). "Jansen metaphyseal chondrodysplasia (JMC) is an ultra-rare autosomal dominant disease that is caused by heterozygous, activating PTH1R mutations resulting in PTH- and PTHrP-independent hypercalcemia and hypercalciuria, leading to nephrocalcinosis and impaired renal function later in life." (PMID 39950977, 2025).
Hypercalcemia (continued). "Hypercalcemia, characterized by elevated serum Ca levels, is most commonly caused by primary hyperparathyroidism and malignancies that lead to increased bone resorption or ectopic production of parathyroid hormone (PTH)-related proteins." (PMID 39940312, 2025). "PC may occasionally present with acute symptoms, including encephalopathy, vomiting, cardiac arrhythmia, and acute renal failure, all associated with a significant rise in PTH levels and severe hypercalcemia, the so-called parathyroid crisis." (PMID 41465801, 2025). "Measuring PTH is therefore part of evaluating cancer-associated hypercalcemia." (PMID 41367907, 2025). "Similarly, in our case report, the patient presented with non-PTH-associated hypercalcemia, polyuria, metabolic alkalosis, hypercalciuria, and acute deterioration of kidney function." (PMID 40520830, 2025). "Instead, hypercalcemia in malignancies is usually associated with low serum PTH." (PMID 39851484, 2025). "At first glance, both causes of hypercalcemia differ clearly in concomitant PTH concentrations." (PMID 41009532, 2025). "In a first step, PTH-dependent and -independent causes of hypercalcemia can be easily separated." (PMID 41009532, 2025). "In iguanian lizards, injection of PTH causes acute hypercalcemia and sometimes hyperphosphatemia and may elevate in response to metabolic or nutritional challenges and stress." (PMID 40501859, 2025). "Persistent hypercalcemia with elevated or inappropriate PTH is a hallmark of PHPT." (PMID 40822048, 2025). "Conversely, PTH-independent hypercalcemia, which is associated with suppressed PTH levels, may arise from malignancy, prolonged immobilization, hyperthyroidism, vitamin D intoxication, or granulomatous disease." (PMID 40284609, 2025). "While tertiary HPT with an altered set point for PTH secretion may explain hypercalcemia in CKD dogs, its underlying mechanisms in AKI are more challenging to elucidate, in the absence of malignancies or primary hyperparathyroidism." (PMID 40005891, 2025). "Both duration of Li administration (hyper i-PTH: ρ = 0.260,p=0.010 and hypercalcemia: ρ = 0.206,p=0.044) and serum Li concentration (hyper i-PTH: ρ = 0.274,p=0.006 and hypercalcemia: ρ = 0.232,p=0.022) showed significant and positive associations with hyper i-PTH and hypercalcemia." (PMID 40747083, 2025). "The National Kidney Foundation-Dialysis Outcomes Quality Initiative (NKF-DOQI) suggest parathyroidectomy should be recommended in patients with severe HPT, with persistent serum levels of PTH > 800 pg/mL, with associated hypercalcemia and/or hyperphosphatemia that is refractory to medical therapy." (PMID 40455298, 2025). "Based on the underlying mechanisms, tumor-induced hypercalcemia can result from osteolytic bone destruction, excessive secretion of PTHrP, or increased activation of 1,25-dihydroxyvitamin D. These mechanisms are generally associated with suppressed PTH levels." (PMID 41287694, 2025). "Therefore, a possible recovery of parathyroid activity can be excluded, and a PTH-independent cause of hypercalcemia had to be investigated." (PMID 39851484, 2025). "A normal to high PTH concentration in the face of hypercalcaemia is considered diagnostic for pHPT." (PMID 40169934, 2025). "Myomas can cause hypercalcemia during pregnancy due to PTH-rp production by estrogen stimulation." (PMID 39148641, 2024). "PC is a rare endocrine malignancy that causes PTH-mediated hypercalcemia." (PMID 39011405, 2024). "Nevertheless, PTH might be found to be elevated (as suggestive for the biological confirmation of primary hyperparathyroidism) or suppressed (as seen in hypercalcemia of malignancy which is associated with cancers of different origins)." (PMID 38928056, 2024). "Notably, the renal 1 alpha-hydroxylase (1α-OHase [CYP27B1]) enzyme is tightly regulated physiologically via feedback loops related to circulating levels of calcium, PTH, and 1,25(OH)2D3 to limit the risk of hypercalcemia." (PMID 39408285, 2024).